INS (insulin)
Diseases named in the same sentence as INS in open-access papers (continued):
Sharing a sentence is not in itself a finding about the gene and the disease.
diabetes (continued). "Conversely, high selenium concentrations in the human body may interfere with insulin signaling, which is critical to the regulation of glucose levels and the prevention of diabetes." (PMID 27142520, 2016). "The strong relationship between decreased insulin sensitivity and women infertility observed in diabetics and PCOS women suggests that the amount and quality of carbohydrates in diet might influence reproductive functions." (PMID 26875986, 2016). "In the multivariate linear regression model corrected for blue-collar work, the following variables were independently associated with SKILLD: schooling (B=0.193; p=0.003), use of insulin (B=1.326; p=0.004), duration of diabetes (B=0.053; p=0.022), and SAHLPA-18 score (B=0.108; p=0.021)." (PMID 28076599, 2016). "In order to understand diabetes, you need to know how the insulin factory operates." (PMID 27007444, 2016). "Mice with β-cell-specific HDAC3 deletion displayed decreased pancreatic insulin content, disrupted glucose-stimulated insulin secretion, with intermittent spontaneous diabetes and dramatically enhanced susceptibility to STZ-induced diabetes." (PMID 27542279, 2016). "Diabetes mellitus is a multiple etiology metabolic disorder with abnormalities in the metabolism of carbohydrate, fat and protein, being characterized by chronic hyperglycemia and defects in insulin secretion, insulin action, or both." (PMID 28025494, 2016). "On the other hand, fetal exposure to intrauterine hyperglycemia is associated with abnormal insulin secretory responses and increased risk of early-onset diabetes, independent of genetic susceptibility and maternal diabetes types." (PMID 27796780, 2016). "Beta-cells are very sensitive and are the only cell type that can produce, store, and release insulin; when they fail or are destroyed or affected, the metabolism is impaired and the onset of diabetes may occur." (PMID 27087124, 2016). "Improving insulin sensitivity may also ameliorate BCAA metabolism, resulting in reduced diabetes risk." (PMID 27898682, 2016). "Our in vitro findings suggest that LIGHT may contribute to the progression of type 2 diabetes mellitus by attenuating insulin secretion in pancreatic islet cells and by contributing to vascular inflammation." (PMID 27421726, 2016). "After one year, the patient developed diabetes, needing insulin therapy." (PMID 27928440, 2016). "Our findings suggest that diabetes therapy through glucagon suppression would be unsafe if exogenous insulin has to be supplemented, but may be beneficial in patients with sufficient residual insulin action." (PMID 27092792, 2016). "Death or dysfunction to β-cells and a reduction or absence of insulin secretion is the main cause of diabetes." (PMID 27681078, 2016). "Our results suggest that BDDE as a new PTP1B inhibitor improves glucose metabolism by stimulating the insulin signaling and could be used in the treatment of type-2 diabetes mellitus." (PMID 26808535, 2016). "Besides, we believe that the period of using insulin or oral antidiabetic drugs and the age of diabetes is also important on the treatment success of type 2 diabetes." (PMID 27186461, 2016). "We investigated the association of the Finnish Diabetes Risk Score (FINDRISC) with insulin secretion, insulin sensitivity, and risk of type 2 diabetes, drug-treated hypertension, cardiovascular (CVD) events and total mortality in a follow-up study of the Metabolic Syndrome in Men (METSIM) cohort." (PMID 27851812, 2016). "We hypothesize that an adjunctive therapy that reduces insulin demand by increasing insulin sensitivity will improve the efficacy of an immunotherapy in reversing diabetes." (PMID 27874076, 2016). "Clinicians may be uncertain regarding the optimal strategy for insulin intensification or favor resorting to less widely used treatment approaches to meet the needs of individual patients, as personalized diabetes management is becoming important." (PMID 27761472, 2016).
diabetes (continued). "Diabetes is characterized by defects in glucose homeostasis and insulin function." (PMID 26901856, 2016). "Moreover, insulin injection is a clinically-approved, effectual and widely received way to regulate blood glucose in diabetes and/or NAFLD patients." (PMID 27104558, 2016). "Although insulin and oral antidiabetic drugs are widely used for the treatment of diabetes, a nutritional or traditional approach could yield better outcomes." (PMID 28197509, 2016). "Such situation has already been described, for example, by Sone and Kagawa, who found that the compensatory proliferation of pancreatic cells driven by insulin resistance resulted in an elevated fraction of senescent cells, which led to even deeper deterioration of insulin activity and diabetes." (PMID 27994710, 2016). "Diabetes developed in all patients and insulin was required to achieve normoglycemia." (PMID 26758964, 2016). "By reducing the basal insulin whether through the basal rates in the pump or by reducing the dose of long-acting insulin, it is possible to improve the Diabetes control and minimize weight gain." (PMID 27777901, 2016). "The high ranking of tolazamide in the insulin sensitivity, islet cell, and β cell models was based on binding assay results for the ATP-sensitive potassium inwardly rectifying channel (KCNJ11) gene, which is commonly associated with diabetes of genetic origin." (PMID 26978842, 2016). "This is not always the case, however, and products might be associated exclusively with a particular condition (for example, insulin with diabetes)." (PMID 26918439, 2016). "Diabetes care trajectories imply that when insulin therapy needs to be initiated, patients are entitled to multidisciplinary care that includes education from a certified diabetes educator and an annual consultation with an endocrinologist, in addition to the regular GP visits." (PMID 27727281, 2016). "In the index patient, diabetes had been diagnosed 3 years before the first pregnancy and she developed obstetric diabetic complications during all of her four pregnancies, which were treated with insulin." (PMID 27142837, 2016). "Numbers of therapies have been used to improve the status of diabetes by different mechanisms such as inhibition of carbohydrate metabolizing enzymes, manipulation of glucose transporters, β-cell regeneration, and enhancing the insulin releasing activity." (PMID 26925100, 2016). "Type 1 diabetes mellitus is due to the body’s failure to produce enough amount of insulin." (PMID 28330164, 2016). "Several with diabetes had switched from a regime of two injections per day at fixed times, with set mealtimes, to a more flexible regime of injecting around the times and type of food they ate, using a combination of fast‐acting and slow‐acting insulin." (PMID 26140336, 2016). "Moreover, it has been reported that high circulating FFA levels in turn aggravated the development of diabetes by prompting beta-cell dysfunction and insulin resistance." (PMID 27669240, 2016). "In the present analysis, the baseline characteristics suggest that the vast majority of the participants were already on an intensive insulin therapy regimen and had remarkably better glycaemic control at baseline than the participants in the diabetes education trials cited above." (PMID 26799064, 2016). "Interestingly the insulin levels in Fukuoka men with diabetes at 6.6 μIU/mL were less than 40% of the values observed in Framingham men with diabetes at 19.0 μIU/mL." (PMID 27830830, 2016). "This would suggest that these co-morbid conditions may further contribute to cognitive impairment through various pathophysiologic processes; for example, in diabetes mellitus, the brain may itself be affected directly by insulin resistance." (PMID 31022800, 2016). "In the future, SHLP2 may have a role in the treatment of diabetes because of its insulin-sensitizing effects." (PMID 27070352, 2016). "Insulin is a protein hormone used in the treatment of diabetes." (PMID 26882071, 2016).
diabetes (continued). "Given that insulin increases serine 368 phosphorylation, we sought to determine whether insulin and/or diabetes exerted similar effects on serine 262 phosphorylation." (PMID 27034963, 2016). "Because hypertension was the most important risk factor for cardiovascular disease in the Taiwanese patients with diabetes, it is reasonable to infer that insulin use may increase the development of cardiovascular disease through the effect of hypertension." (PMID 27906989, 2016). "This study contributes to our understanding of the central role of GalR1 in benefit of glucose uptake and insulin sensitivity, offering a possibility that the GalR1 may be taken as a potential therapeutic target for type 2 diabetes mellitus." (PMID 27127795, 2016). "However, there is a paucity of data regarding the knowledge and practice of Ethiopian diabetes patients towards insulin injection device disposal." (PMID 27738637, 2016). "The so-called “Western diet” therefore may promote diabetes by lowering membrane fluidity, hence impairing insulin signaling and other processes." (PMID 27671740, 2016). "Breakthrough cellular approaches aim to generate stem-cell-derived insulin producing cells, which could make diabetes cellular therapy available to millions." (PMID 27400873, 2016). "Diabetes mellitus (DM) is a chronic disease and characterized by insufficient insulin activity." (PMID 27187435, 2016). "In the present studies insulin was administered 2 weeks after induction of diabetes without any loss of animals." (PMID 27253523, 2016). "Thus, the daily NSO treatment in our rat model indicates that NSO has a potential in the management of diabetes as well as improvement of insulin-induced signaling." (PMID 27579151, 2016). "Since the advent of insulin, the improvements in diabetes detection and the therapies to treat hyperglycemia have reduced the mortality of acute metabolic emergencies, such that today chronic complications are the major cause of morbidity and mortality among diabetic patients." (PMID 27652272, 2016). "Another novel concept is that chronic inflammation may result in local disruption of insulin signaling, leading to the initial development of both micro- and macrovascular complications of diabetes." (PMID 26989334, 2016). "Neither diabetes mellitus nor preadmission insulin or metformin use are associated with altered disease presentation, outcome or host response in patients with sepsis requiring intensive care." (PMID 27495247, 2016). "Diabetes mellitus is attributed to ineffective use of insulin in the body." (PMID 27995147, 2016). "While not directly comparable, self-reported data from national surveys suggest 68.5% of all adults with diagnosed diabetes (type 1 and type 2, insured and uninsured) had two or more A1c tests in 2010; 62.8% had a dilated eye exam; and 85.6% took medication for diabetes (pills, insulin, or both)." (PMID 27895533, 2016). "In addition to diet control and exercise, type 2 diabetic patients commonly require diabetes medications and insulin." (PMID 27904436, 2016). "Recent studies indicated that the inability of insulin to restore sevo-postC cardioprotection in diabetes might be attributed to diabetes-induced STAT3 mediated inhibition of PI3K signaling." (PMID 26783539, 2016). "Importantly, biphasic insulin release is disturbed in diabetes, which has been suggested to have its origin within the pancreatic β-cells, likely because of dysfunctional exocytosis." (PMID 27907065, 2016). "In the diabetes cohort, more participants were insulin pumper users." (PMID 26879273, 2016). "Most (62.7%) patients used oral medications to control diabetes and the rest took insulin." (PMID 27921026, 2016). "Endothelial and insulin signalling pathways crosstalk each other and therefore the relationship between endothelial function and insulin metabolism is very important in disorders, such as hypertension, obesity, or diabetes." (PMID 27413253, 2016).
diabetes (continued). "However, further investigation is warranted to include more brain areas to examine insulin signaling and to verify the critical role of central insulin action in developing prediabetes and subsequent diabetes in individuals with MDD." (PMID 27274905, 2016). "Satisfaction with current antidiabetic treatment was associated with improved glycaemic control among non-insulin-treated type 2 diabetic patients, but gender and participation in a diabetes education program were not." (PMID 26798654, 2016). "For instance, blacks are reported to be more insulin resistant compared to Caucasians, whereas South Asians are reported to be more insulin sensitive, but have poorer insulin secretion as compared to Caucasians, indicating differing mechanisms contributing to diabetes among ethnicities." (PMID 27938404, 2016). "The hormones insulin and glucagon both play important roles in the development of diabetes." (PMID 27190125, 2016). "This has led to increased interest in the role that insulin might play in the nervous system and it is becoming very clear that there is a strong link between diabetes and Alzheimer's disease." (PMID 28066166, 2016). "Older age, longer diabetes duration, male sex, and use of insulin, sulfonylurea, calcium channel blockers, aspirin, ticlopidine, clopidogrel and dipyridamole were significantly associated with a higher risk in sitagliptin users, but dyslipidemia and use of metformin and statin were protective." (PMID 27409676, 2016). "For most patients with diabetes, exercise and dietary management will prove insufficient to maintain euglycemia, and roughly 80% at some point will require either oral hypoglycemic agents and/or insulin injections for satisfactory blood glucose control." (PMID 27110686, 2016). "Ketoacidosis resolved after increasing dextrose and insulin doses supporting the hypothesis that SGLT-2 inhibitors may lead to hypoinsulinemia." (PMID 27375734, 2016). "Also, dams were partially treated with insulin to mimic treatment of diabetes after a screening glucose tolerance test at 24–28 weeks gestation in pregnant women." (PMID 27518105, 2016). "The predictive markers for the progression to insulin-requiring diabetes have been unclear." (PMID 27177031, 2016). "Studies in cells, animals, and patients suggest that it may be useful in common neurodegenerative diseases, such as Parkinson’s and Alzheimer’s diseases, as well as in insulin-resistant states, such as trauma, heart failure, and diabetes." (PMID 27528626, 2016). "For example, several researchers have indicated that a fasting plasma insulin level (FINS) of 39 mU/mL or greater was associated with a 31% increased risk of cardiovascular events in individuals without diabetes." (PMID 26770991, 2016). "Excess free fatty acids reduce the hepatic clearance of insulin, which may lead to insulin resistance, hyperinsulinemia, and diabetes." (PMID 27340824, 2016). "Also, the side effects of this statin including insulin resistance level, hepatic dysfunction, muscle injury, renal dysfunction, and the incidence of overt diabetes will be within the acceptable range." (PMID 27872642, 2016). "First, among a national cohort of veterans with diabetes, 50 % of metformin initiators intensified therapy by 4 years of follow-up and while sulfonylurea was the most common addition, there was an increase in the proportion adding insulin over time." (PMID 27255309, 2016). "Over half of the patients in the study were treated with insulin and all subjects had diabetes." (PMID 27612202, 2016). "The Kir6.2 protein along with another protein SUR1 encoded by the ABCC8 gene located next to the KCNJ11 gene forms the KATP channel which modulates insulin production and secretion through glucose metabolism and is the target of sulphonylurea drugs used for treating diabetes." (PMID 28330327, 2016). "On the other hand, only diabetes and age, but not obesity or fasting insulin, were associated with lower cognition, MMSE." (PMID 27642517, 2016).
diabetes (continued). "The aim of this study was investigate the relationships between the three frequently used sulphonylureas, prescribed as dual therapy next to metformin, and the time needed to treatment intensification with either insulin or oral triple therapy in patients with type 2 diabetes mellitus." (PMID 27327605, 2016). "This could be explained by the fact that insulin users, especially type 2, had worse diabetes or that insulin has a direct neurotoxic effect." (PMID 27449153, 2016). "Finally AUC-insulin was negatively correlated with DI, suggesting a correlation with possible subsequent β-cell function failure and development of diabetes." (PMID 26989412, 2016). "Insulin allergy is an important adverse effect of insulin treatment in patients with diabetes." (PMID 27456688, 2016). "We sampled from graduates who had recently completed structured education in flexible insulin self management education to explore the specific features that this specific type of insulin user would want from a phone based app to support day to day diabetes management." (PMID 27629774, 2016). "Historically, due to acute lack of insulin production, type 1 diabetes mellitus (T1DM) was associated with severe emaciation diagnosis." (PMID 27429649, 2016). "Adequate and stable basal insulin levels are a critical component of diabetes therapy because they regulate hepatic glucose output, which is essential for proper maintenance of glucose homeostasis during the diurnal cycle and inter-meal periods and they help to minimize nocturnal hypoglycemia." (PMID 27528391, 2016). "Insulin action depends on three major physiological processes: insulin sensitivity, insulin secretion, and insulin clearance, and each one of these processes may be influenced by several pathophysiological conditions, such as obesity and diabetes." (PMID 27467214, 2016). "The notion of ER stress in diabetes originated after several studies concluded that during the pre-diabetic period, β cells entered a hyper-active mode of pro-insulin synthesis, which led to an increase in protein misfolding; the mis-folded proteins eventually accumulated at the ER and caused ERS." (PMID 27092078, 2016). "Therefore, we have quantified miR-375 in sera from children population at onset of T1D (immediate insulin-requiring diabetes with at least one positive autoantibody) before subcutaneous insulin treatment." (PMID 27314045, 2016). "Weight excess was not specifically associated with intensity of insulin treatment and diabetes duration in this large group of individuals with type 1 diabetes." (PMID 27011769, 2016). "We did not exclude gestational diabetes requiring insulin, since these women have a high risk of later developing diabetes." (PMID 26900131, 2016). "As adjustment for diabetes did not substantially influence risk estimates, factors in addition to insulin signaling appear to be influencing breast cancer risk in overweight and obese populations." (PMID 27338371, 2016). "In fact, in diabetes studies, researchers use many different ways to implement insulin therapies." (PMID 27504460, 2016). "Less hygienic use of blood glucose monitoring equipment such as blood glucose meters, lancets, finger stick devices or other diabetes-care equipment such as syringes or insulin pens by self-administration often exposes the diabetic patient to Hepatitis B infection." (PMID 28638894, 2016). "Given the fact that impaired insulin secretion is needed for the conversion to diabetes we hypothesized that the FINDRISC is also a marker of impaired insulin secretion and insulin resistance related traits." (PMID 27851812, 2016). "Moreover the insulin levels in Fukuoka women with diabetes were significantly lower than those values in Framingham NGT women (P < 0.001) and values for HOMA-IR in Fukuoka women with diabetes were similar to Framingham NGT women." (PMID 27830830, 2016).